LEP (leptin)
Diseases named in the same sentence as LEP in open-access papers (continued):
Sharing a sentence is not in itself a finding about the gene and the disease.
Obesity (continued). "Leptin, which is primarily produced by adipose tissue and is the product of the obesity gene, controls food intake and energy expenditure, fatty acid metabolism of skeletal muscle, and hepatic glucose synthesis." (PMID 35734805, 2022). "Taken together, these observations suggest that reduced access of leptin into the CNS due to the depletion and/or desensitization of tanycytes, coupled with neuronal loss of leptin receptors may ultimately be responsible for the leptin resistance that characterizes common obesity." (PMID 35527735, 2022). "Inhibiting leptin using specific antibodies or antagonists also substantially reduces blood pressure in mice with diet-induced obesity and alleviates cachexia in CKD mice." (PMID 36726470, 2022). "The prevalence of depression is known to be increased in the setting of obesity, a condition that promotes inflammation as well as resistance to insulin and leptin." (PMID 35911213, 2022). "An important aspect of diet-induced obesity is the occurrence of resistance to the effects of exogenous leptin and also ghrelin." (PMID 35627229, 2022). "OT intervention repressed leptin expression, which was consistent with a population-based study where leptin levels were negatively correlated with obesity traits." (PMID 35967777, 2022). "Leptin, which is a hormone secreted by adipocytes and elevated in individuals with obesity, is increased in women with endometriosis, UF, and hypertensive disorders of pregnancy, even when analyses are adjusted for BMI." (PMID 35104295, 2022). "The compound KSK-74 significantly compensates for metabolic disturbances that accompany obesity (plasma triglyceride, resistin, and leptin levels), improves glucose tolerance, and protects against adipocyte hypertrophy." (PMID 35806019, 2022). "In addition, the lipid metabolism has been indicated to be affected by circadian rhythm; the decrease in leptin and increase in the ghrelin levels caused by a sleep deficiency could lead to a weight gain, lipid accumulation, and obesity-related metabolic disorders." (PMID 36499163, 2022). "These in vitro findings are consistent with studies conducted in individuals with airway inflammation, where serum levels of both leptin and IL-1β were shown to increase with BMI and were thus higher in subjects with obesity." (PMID 35806353, 2022). "Since leptin decreases body weight and food intake, the synchronicity of raised leptin levels with obesity is generally interpreted as an indication of leptin resistance." (PMID 35655598, 2022). "GM3S KO cells had reduced leptin-dependent STAT3 phosphorylation, which is required for leptin anti-obesity activity, consistently with observations in other KO models that a-series gangliosides positively regulate LepR signaling." (PMID 35628171, 2022). "Together our results strongly suggest that aberrant inflammatory endothelial responses are not mounted by direct SARS-CoV-2 infection of endothelial cells, even in the presence of leptin and other mediators of obesity." (PMID 35837388, 2022). "The impacts of altered placental leptin level/function in offspring of mothers with obesity are a complex process and differ in timing across pregnancy." (PMID 36189369, 2022). "For reasons previously discussed, however, we know that hyperleptinemia is responsible for the leptin resistance seen in common obesity, and for the failure of exogenous leptin to resolve this problem." (PMID 35527735, 2022). "Leptin is considered as a potential marker of obesity and its comorbidities—in particular, type 2 diabetes and CVD—due to its angiogenic and atherogenic effects." (PMID 36499312, 2022). "In this sense, celastrol, a pentacyclic triterpene extracted from the roots of Tripterygium wilfordi, appeared as an interesting anti-obesity compound due to its powerful role as a leptin sensitizer." (PMID 35684076, 2022).
Obesity (continued). "Sleep fragmentation attenuates leptin signalling in the hypothalamus, resulting in consequential high-calorie food intake enhancing obesity." (PMID 36359273, 2022). "In vitro findings from our laboratory demonstrate that both high glucose and high leptin, at concentrations reflective of diabetes and obesity respectively, stimulate TSP-1 expression in human aortic SMC primary cultures." (PMID 36505365, 2022). "Between all adipokines, two are of particular importance in obesity and cancer, and will be more thoroughly discussed: leptin and adiponectin." (PMID 35164764, 2022). "Leptin is chronically produced by AT in individuals with obesity and interferes with IFN signaling by increasing Suppressor of Cytokine Signaling 3 (SOCS3)." (PMID 36466818, 2022). "Leptin is described as another major driver in the context of obesity-induced angiogenesis, which stimulates the expression of VEGF by activating the hypoxia-inducible factor 1-alpha HIF1α and NFĸB pathways." (PMID 36010901, 2022). "Our understanding of the prospective link between obesity and CRC stems from the potential relationship of LEP genetics with the main pathogenic pathways and the molecular mechanisms of these associations, in the context of inconsistent and contradictory data." (PMID 35563103, 2022). "Much information on the importance of leptin in the pathogenesis of overweight and obesity comes from genetic studies." (PMID 35684517, 2022). "To summarize, these results suggest that the role of leptin in regulating bone in obesity remains controversial." (PMID 35883424, 2022). "Higher concentrations of Leptin, insulin, and C-peptide are strongly associated with excessive GWG and obesity." (PMID 36224521, 2022). "The modulation of leptin/adiponectin in breast milk by promoting changes in the maternal dietary pattern can be of interest in preventing obesity in offspring." (PMID 35806240, 2022). "Obesity induced chronic inflammation leads to the inhibition of leptin signalling and accordingly to leptin resistance." (PMID 36670938, 2022). "As obesity develops, the increased locally released leptin levels from MAT stimulate mesenchymal stem cells (MSCs), acting through the leptin receptor (LepR) to inhibit osteogenesis and promote adipogenesis." (PMID 35011721, 2022). "Natural killer (NK) cells, which are a critical part of the innate immune system, are impaired in patients with obesity through elevated circulating levels of leptin." (PMID 35435599, 2022). "Generally, circulating leptin concentrations are higher in obesity and metabolic syndromes, including type 2 diabetes, hypertension, or dyslipidemia, in conjunction with a decrease in adiponectin levels in the blood." (PMID 36232660, 2022). "Levels of this aldehyde can rise with fat accumulation which can initiate an ER stress response and further increase its production, and can then lead to impaired leptin signalling and obesity." (PMID 35563589, 2022). "Eating within two hours of bedtime is, however, regarded as a dietary habit that promotes obesity due to fat accumulation that results from insulin secretion and action of the appetite hormone leptin." (PMID 35329088, 2022). "Mice models of obesity also highlight the role of leptin in survival and maintenance of cancer stem cells, complemented by its regulation of NANOG, SOX2, and OCT4." (PMID 35164764, 2022). "Insulin resistance and leptin levels are increased in hypothyroid children and adolescents; more in those with obesity." (PMID 35501770, 2022). "With obesity, there is altered levels of catecholamines, glucose, and cytokines such as IFNγ, but also hormones like leptin and insulin." (PMID 36713396, 2022). "Tanycytes appear to be the first cells of the brain to become resistant to leptin in diet-induced obesity, and this alteration is prior to the appearance of metabolic dysfunctions." (PMID 34523036, 2022).
Obesity (continued). "Leptin is one of the most important adipokines, generally considered as an “anti-obesity hormone”, although it displays various abnormal functions in obesity." (PMID 35563103, 2022). "Adipokines like leptin and adiponectin secreted by adipose tissue modulate insulin resistance (IR), appetite, and obesity." (PMID 35501770, 2022). "Efforts of genetic studies to find the genes involved in the energy balance have led to detection of several obesity-related genes including the leptin, melanocortin-4 receptor (MC4R), and fat mass and obesity-associated (FTO)." (PMID 36440355, 2022). "Increased circulating leptin and resistin levels with decreased adiponectin levels are characteristics of obesity." (PMID 36500974, 2022). "In obesity, the leptin level is elevated due to increased adipocytes and also due to leptin resistance, which is characterized by a lack of appetite suppression despite high leptin concentrations." (PMID 35407646, 2022). "Strong associations were identified of these phospholipids with triglycerides, but also with obesity related traits (e.g., waist, waist-hip ratio, total fat percentage, BMI and leptin), T2D and related traits (e.g. glucose, HOMA-IR and insulin)." (PMID 35022422, 2022). "The co-administration of CCK with GLP-1 and leptin substantially enhances metabolic benefits under conditions of obesity and diabetes." (PMID 35334929, 2022). "In the face of sustained leptin release, however, the central receptors downregulate, which leads to leptin resistance, over-eating and obesity." (PMID 36005607, 2022). "The analysis of obesity-associated serum parameters showed that CAF feeding increased glucose, triacylglycerides, insulin, HOMA-IR, leptin, adiponectin, and the leptin/adiponectin ratio compared to STD feeding." (PMID 36379981, 2022). "Animal studies suggest that the improper timing of food intake, as well as high-fat diets (HFD), disrupt leptin levels, leading to overeating and sleep deprivation, and thus play a role in the development of obesity, cancer, and metabolic consequences." (PMID 36291899, 2022). "LEP is an adipokine secreted by adipocytes that reflects the degree of obesity; a decline in the level of LEP revealed the anti-obesity effect of IH in HFD-fed mice." (PMID 36079733, 2022). "Studies reported that the expression level of fat mass and obesity associated gene (FTO) and pleomorphic adenoma gene 1 (PLAG1) genes associated with obesity was significantly related to the concentration of leptin." (PMID 35498804, 2022). "In particular, leptin was identified as the product of the obese (ob) gene following the characterization of monogenic obesity (ob/ob) mice model." (PMID 36452324, 2022). "In a group of adolescent females with obesity, the leptin/adiponectin ratio significantly decreased after 12 weeks of high-intensity training, and the decrease was even greater in high-intensity training combined with plyometric exercises." (PMID 36364954, 2022). "In particular, many epidemiological and experimental observations have identified leptin, whose serum levels increase proportionally to adipose tissue mass, as a key actor for the molecular connection between obesity and breast cancer." (PMID 36361728, 2022). "The activation of these inflammatory pathways is crucial because the activation of IKKβ/NF-κB influences leptin and insulin metabolism, affecting even the processes of glucose intolerance in obesity." (PMID 35422689, 2022). "Leptin as a hormone with a key role in food intake and body weight homeostasis is commonly elevated in obesity, a condition known as hyperleptinemia." (PMID 36364892, 2022). "Physiological changes concurrent with obesity, such as increases in orexigenic acetyl-CoA binding protein and disruption of leptin- and ghrelin-mediated appetite signaling cues, provide further barriers for adherence to restrictive diets." (PMID 35752704, 2022).
Obesity (continued). "These mice lack the gene for functional leptin, a satiety hormone, and quickly develop severe obesity and insulin resistance." (PMID 36077188, 2022). "Although promising, increased leptin level does not lead to decreased food intake and increased EE in individuals presenting with obesity, which is explained by a state of leptin resistance." (PMID 34928408, 2022). "Celastrol is a natural compound acting as a leptin sensitizer with anti-obesity effects when administered in adult animals." (PMID 35684076, 2022). "Previous studies have found that overexpression of RAP1GAP has a negative regulatory effect on Rap1, which can enhance the cellular effect of leptin and reduce the production of obesity." (PMID 36090178, 2022). "The 6p11.2 distal deletion includes the SH2B1 gene involved in leptin and insulin signalling and has been shown to have a polymorphic effect on obesity." (PMID 35590413, 2022). "When obesity persists, prolonged stimulation by leptin and circulating free fatty acids, repetitive antigen stimulation, activating stress responses, and hypoxia induce exhaustion of CD4 T cells in VAT." (PMID 36685567, 2022). "Obesity is related to an increase in circulating triglycerides, FFAs, and leptin, in addition to increased weight and fat accumulation." (PMID 35807946, 2022). "Leptin and adiponectin levels correlated well with BMI in hypothyroid children and adolescents with obesity." (PMID 35501770, 2022). "Reportedly, INS and LEP are closely related to obesity, while PTPN11 was identified in the studies of histiocytic sarcoma and Noonan syndrome." (PMID 35529938, 2022). "In this study population, an increase in the mean serum leptin level was observed in obesity group with dominant AA genotype (LEP − 2548G/A)." (PMID 36619235, 2022). "Regarding adipokines, serum leptin was significantly elevated in lean and hypothyroid children with obesity groups compared to the control group, more in hypothyroid children with obesity (P = 0.034)." (PMID 35501770, 2022). "As confirmed by protein chip analyses, KY19334 decreased the expression levels of various adipokines such as angiopoietin‐3, DPP4, IGFBP‐5, leptin, resistin and PAI‐1, which are implicated in obesity‐related insulin resistance." (PMID 35384342, 2022). "Recent studies from our laboratory have documented that global TSP-1 deletion in vivo reduces atherosclerotic lesion burden in ApoE–/– mice in response to both STZ-induced hyperglycemia and exogenous leptin administration, mimicking obesity." (PMID 36505365, 2022). "The activity state of AMPK varies in obesity-high leptin levels will inhibit, while adiponectin (which falls in obesity) will activate." (PMID 36038791, 2022). "The anti-obesity effect of melatonin and sleep has been proved, but the exact therapeutic targets of leptin resistance-induced obesity are yet to be studied." (PMID 35937803, 2022). "Mild obesity appears to improve survival in ALS patients, and obesity affects leptin, which is associated with a lower risk of developing ALS." (PMID 34935299, 2022). "Leptin is mainly involved in the central control of energy metabolism and obesity but also plays a key role in other physiological systems and diseases, including autoimmune diseases, human dental pulp, bone metabolism, or cardiovascular diseases." (PMID 36555171, 2022). "Despite increased levels of leptin being secreted by white adipose tissue (WAT) in obesity, dual actions of this adipokine on bone is observed." (PMID 35883424, 2022). "This 80 kb deletion is consistent with previous observations that heterozygous human carriers of leptin or LEPR mutations are predisposed to overweight and obesity." (PMID 35456010, 2022). "In general, FIRKO mice appeared to have an improved metabolic phenotype, were protected from hyperphagic obesity, had decreased adiposity, improved i.p. glucose tolerance, and altered leptin expression." (PMID 34801552, 2022).
Obesity (continued). "Leptin-induced vascular endothelial dysfunction is another mechanism that links altered adipokine secretion in obesity with impaired renal function." (PMID 35406070, 2022). "Previous studies have reported that HFD-induced obesity intensifies psoriasiform dermatitis and demonstrates the potential involvement of leptin." (PMID 35457132, 2022). "Obesity and related chronic inflammation states are often accompanied with increasing leptin concentrations and consequently lead to leptin resistance further fueling metabolic disorders." (PMID 35154697, 2022). "Cultured primary VMH neurons harvested from a leptin resistant, polygenic rat model of obesity treated with IL-6 for 5 days were found to restore leptin-sensitivity manifested primarily by increased expression of leptin receptor expression." (PMID 35050175, 2022). "Compared with leptin and other pro-inflammatory cytokines, adiponectin shows an opposite trend in conditions of obesity." (PMID 35909571, 2022). "Leptin has an important role in the long-term regulation of body weight; increased leptin levels were found in the plasma of patients with obesity, suggesting a resistance to hormone effects on target organs when excessively produced." (PMID 35214069, 2022). "Most of the studies have analyzed the relationship between leptin and lymphoma, obesity and lymphoma, or obesity and leptin." (PMID 36555171, 2022). "While these studies point to leptin’s pro-fibrotic role, the impact of increased serum leptin levels in obesity on asthma pathobiology is less well understood." (PMID 35610699, 2022). "Sh2b1 knocking out mice had disrupted metabolic phenotypes including obesity and leptin resistance, while restoring SH2B1β in neurons attenuates these metabolic disorders by improving leptin signaling pathways." (PMID 33826123, 2022). "In contrast, subsequent studies showed that acute sleep deprivation or sleep restriction significantly increased morning leptin in healthy women and women with obesity, as well as in a group of healthy young men and women." (PMID 35163627, 2022). "An association between leptin, adiponectin, hsCRP and IMT was found in youth with obesity in other studies." (PMID 36012972, 2022). "One of the strongest links found thus far between obesity and autoimmunity have come from studies examining the role of leptin on immune function." (PMID 36479348, 2022). "This is mainly due to bone protective effects of high insulin level as the result of insulin resistance, mechanical tension of excess weight on bones, and elevated leptin levels in T2DM patients with concurrent obesity." (PMID 36578470, 2022). "Conversely, in a separate mouse model which allowed manipulation of circulating leptin levels during discrete time windows, mice who experienced transient hyperleptinemia from PND0 to PND22 showed a greater susceptibility to develop obesity as adults." (PMID 36619540, 2022). "Together our in vitro results suggest that aberrant inflammatory endothelial responses are not mounted by direct endothelial infection of SARS-CoV-2 even in the presence of leptin and other mediators of obesity." (PMID 35837388, 2022). "An inverse relationship between leptin and adiponectin has been reported in adults with T2D and in patients with obesity and coronary artery disease." (PMID 36010052, 2022). "The expansion of the adipose tissue in obesity is positively correlated to leptin synthesis and secretion." (PMID 35937866, 2022). "In contrast, leptin, which is increased in patients with obesity, has receptors on osteoblasts and appears to directly stimulate osteoblast cell differentiation and inhibit osteoclast cell differentiation." (PMID 35955431, 2022). "In mice with diet induced obesity, serum testosterone and LH concentrations decrease, and the serum concentration of leptin increases, while the expression of leptin receptor, kisspeptin and the kisspeptin receptor GPR54, in hypothalamic neurons decreases." (PMID 35834069, 2022).